IL1B (interleukin 1 beta)
Diseases named in the same sentence as IL1B in open-access papers (continued):
Sharing a sentence is not in itself a finding about the gene and the disease.
Hyperglycemia (continued). "Hyperglycemia induced the degradation of IκBα and NF-κB activation and as a result increased infiltration of macrophages (52%) as well as increased proinflammatory cytokines: TNF-α and IL-1β." (PMID 21663638, 2011). "Under metabolic stress conditions, such as obesity and hyperglycemia, these macrophages can be activated through receptors such as TLR4 and RAGE, triggering the NF-κB and NLRP3 inflammasome signaling pathways and promoting the release of pro-inflammatory cytokines such as IL-1β and TNF-α." (PMID 41321403, 2025). "Furthermore, chronic hyperglycaemia initiates the secretion of a damage-related S100A8 molecule (calgranulin A) from pancreatic islets that in turn increase macrophage infiltration leading to the production of pro-inflammatory cytokines, including IL-1β." (PMID 38962295, 2024). "DAMPs (damage-associated molecular patterns), such as LDL, cholesterol crystals, calcium pyrophosphate crystals, uric acid crystals, hyperglycemia, disrupted blood flow, and hypoxia, activate the NLRP3 inflammasome, which produces interleukin-1β (IL-1β) via caspase-1-mediated cleavage of pro-IL-1β." (PMID 38791250, 2024). "Hyperglycemia leads to pro-oxidative substance generation, results in oxidative stress and PARP activation, affects nuclear factor-κB activation, and subsequently leads to the secretion of inflammatory substances, including COX-2, IL-1β, and IL-6 by Schwann cells." (PMID 37960130, 2023). "Previous studies revealed that deletion or overexpression of NLRP3 had no change in IL-1β release and severity of pancreatic injury and could not prevent β-cells from pyroptosis during hyperglycemia." (PMID 35265148, 2022). "In the present study, high levels of IL-1β and NLRP3 inflammasome activation were observed in the hippocampus of the db/db mice and HG-induced hippocampal neurons, suggesting that hyperglycemia could activate NLRP3 inflammasome and induce hippocampal inflammation." (PMID 29507694, 2018). "Our results suggest that hyperglycemia-induced upregulation of IL-1β independent of resident immune cells may promote a pro-inflammatory microenvironment in vitro." (PMID 30470798, 2018). "Production of bioactive IL1β by the NLRP3 inflammasome requires a two‐step process involving initial priming from the toll‐like receptors (TLR) by lipopolysaccharide (LPS) and subsequent activation by hyperglycemia, saturated fatty acids such as palmitate, ROS, oxidized LDL, or cholesterol crystals." (PMID 28544264, 2017). "Reduced H3K9 methylation was also observed at the IL-1β and TNF-α promoters in LPS-treated THP-1 cells, at the MMP-9 promoter in phorbol 12-myristate 13-acetate–treated HeLa cells and at the NF-κB-p65 promoter in a model of transient hyperglycemia in bovine aortic endothelial cells." (PMID 24886859, 2014). "It is intriguing to speculate that the lack of IL-1β secretion by glomerular cells protects the glomerulus from inappropriate inflammation potentially induced by immune complexes, hyperglycemia, oxidative stress, or immunostimulatory crystals." (PMID 22046355, 2011). "Moreover, hyperglycemia could impede the expression of HIF‐1α, an anti‐inflammatory hypoxia‐inducible factor‐1α, thereby disrupting the NLRP3/IL‐1β signaling pathway and influencing T lymphocyte differentiation, thereby compromising the body's anti‐inflammatory response against Aspergillus." (PMID 40860300, 2025). "To test this hypothesis, we quantified the gene expression of macrophage-secreted cytokines (IL-1β, IL-6, TNF-α, IL-10) and chemokines (CCL2) in the lacrimal gland, conjunctiva and cornea of non-diabetic normoglycemic mice and diabetic mice with 7, 14, and 28 days of hyperglycemia." (PMID 39749321, 2024). "Interestingly, our data show that, though hypoglycemia could also drive a M1 polarization shift, unlike hyperglycemia-induced programming, these macrophages did not secrete increased levels of IL-1β and MCP-1." (PMID 32806763, 2020).
Hyperglycemia (continued). "Moreover, persistent hyperglycemia results in the glycosylation of myelin protein, which changes the antigenicity of neurons, promoting activation of glial cells, leukocyte infiltration, and release of inflammatory cytokines, including TNF-α and IL-1β, leading to neuroinflammation." (PMID 32659952, 2020). "Specifically, hyperglycemia may facilitate the synthesis of advanced glycation end products (AGEs) that induce oxidative stress via RAGE, activating NF-κB that initiates and regulates inflammation by synthesizing proinflammatory cytokines, including TNF-α, IL-1β, and IL-6." (PMID 26074994, 2015). "For instance, hyperglycemia per se, regardless of the presence/absence of concurrent endotoxemic insult, depressed the expression of TNF-α mRNA, but augmented the IL-1β and IL-6 mRNA expression in MLNs." (PMID 26207186, 2015). "In line with this idea, recent in vitro studies using human endothelial cells, demonstrated that hyperglycemia alone was not sufficient to induce expression of VCAM-1, but it significantly enhanced the induction of endothelial VCAM-1 elicited by IL-1β." (PMID 20856927, 2010). "This study showed that blood glucose, insulin, HOMA-IR, TG, LDL-C, TCHO, IL-1β, TNF- α showed marked elevation in T2D mice, suggesting that there is hyperinsulinemia and IR in T2D, the body is in an inflammatory state, insulin can not be used normally, which is manifested as hyperglycemia." (PMID 41098781, 2025). "Such a potentiating effect of high D-glucose was not restricted to IL-1β, as it was also observed for the pro-inflammatory cytokine TNF-α, whose levels are elevated in the circulation of diabetic patients and whose release to the circulation is promoted by hyperglycemia." (PMID 20386708, 2010).
melanoma (324 papers, 2006 to 2025). A malignant, usually aggressive tumor composed of atypical, neoplastic melanocytes. "CCK-8 assay illustrated loss of IL1B significantly inhibited the viability of vemurafenib-resistant A375R melanoma cells, while overexpression of IL1B strongly increased the viability of vemurafenib-resistant A375R cells." (PMID 41145465, 2025). "Constitutive activation of the NLRP3 inflammasome causes late-stage human melanoma cells to spontaneously secrete IL-1β via Caspase 1 processing." (PMID 39201564, 2024). "-Influences IL-1β, IL-6, and IL-33 plasma levels.-Protective against sporadic malignant melanoma.-Increased susceptibility to Mycobacterium tuberculosis infection in HIV-positive patients." (PMID 38920661, 2024). "Further, NLRP3 and IL-1β have been shown to be overexpressed in melanoma samples, and targeting tumor-associated NLRP3 prevents melanoma growth by reducing the expansion of myeloid-derived suppressor cells (MDSCs)." (PMID 39769450, 2024). "Real-time PCR was performed to establish the mRNA level encoding IL6 and IL1β in resistant and control melanoma cell lines (respectively)." (PMID 39175042, 2024). "Following the activation of NLRP3 in melanoma cells, PMN-MDSCs proliferate in response to IL-1β-induced melanoma-associated inflammation, which results in reduced natural killer and CD8 + T cell activity and enhanced Treg cell population in primary tumors." (PMID 38609997, 2024). "We demonstrate that the electrogenic transfer of ICD effector-encoding plasmids into mouse melanoma tumors when combined with intratumoral expression of cytokines IL-1β, IL-12, or IL-18, enhanced anti-tumor immune responses." (PMID 39737979, 2024). "The elevated level of IL-1β in the serum of advanced melanoma patients was associated with higher frequency of MDSCs and Tregs." (PMID 38520006, 2024). "Research involving hepatocellular carcinoma (HCC), gastric cancer, melanoma, multiple myeloma and other malignancies demonstrated a positive association between IL-1β levels and PD-L1 expression." (PMID 37511306, 2023). "Some previous studies in melanoma cell proliferation regulation indicated that NLRP3 was associated with the IL-1β secretion and T cell response suppression in the TME." (PMID 36276158, 2022). "The expression levels of the IL-1β gene or IL-1β protein are associated with the invasiveness and metastasis of melanoma." (PMID 36077992, 2022). "In accordance, melanomas displayed an attenuated growth rate when induced in IL-1 receptor-deficient mice, underpinning the pro-tumorigenic role of IL-1β." (PMID 35406483, 2022). "Here, we demonstrate that nucleotide-binding domain, leucine-rich containing family, pyrin domain-containing-3 (NLRP3) inflammasome activation in melanoma is linked to IL-1β production, inflammation, and immunosuppression." (PMID 33649199, 2021). "Subsequent to NLRP3 activation in melanoma cells, IL-1β induces melanoma-associated inflammation, resulting in immunosuppression." (PMID 33649199, 2021). "For example, melanoma-associated inflammation facilitates tumor progression and, specifically, is linked to IL-1β activity." (PMID 33649199, 2021). "IL-1β has also been shown to be upregulated in many solid tumors, including melanoma, and is associated with angiogenesis, invasiveness, and poor patient survival." (PMID 33466236, 2021). "In this work, we also evaluated the markedly positive association of NLRP3 and IL-1β expression in melanoma and further confirmed the collective roles of both regulators." (PMID 34747716, 2021). "Epigallocatechin-3-gallate was shown to have a vital role in the inhibition of melanoma cell growth at physiological doses and reduced NF-κB activity was linked with decreased IL-1β secretion from melanoma cells." (PMID 32660101, 2020). "We further investigated the mechanisms underlying IL-1β treatment on enhancing stemness of squamous cell carcinoma and melanoma." (PMID 32547321, 2020).
melanoma (continued). "In this study, we determined the impact of IL-1β on the stemness of squamous cell carcinoma and melanoma cells and explored the underlying mechanisms by which IL-1β maintains the stemness of CSCs." (PMID 32547321, 2020). "Expression of mutated BRAF (v-raf murine sarcoma viral oncogene homolog B1) V600E mutation induces the transcription of IL1A and IL1B in papillary thyroid carcinoma cells, melanocytes, and melanoma cell lines and this induction can be inhibited by vemurafenib." (PMID 32635472, 2020). "CM derived from bcl-2 overexpressing melanoma cells treated with IL-1β blocking antibody caused a strong inhibition of M2 macrophage polarization, resulting in significant reduction of M2 (CD206, CCL1, CCL22) and induction of M1 (COX-2 and IL-12) markers." (PMID 32269145, 2020). "Melanoma cultures from this patient (patient 7) were shown to produce high levels of a range of cytokines including IL‐1β, IL‐6, IL‐8, and VEGF, which were associated with constitutive activation of NF‐kB." (PMID 32027447, 2020). "IL-1β has been linked to progression and metastasis of many malignancies, such as melanoma, lung, breast and gastric cancers." (PMID 31480312, 2019). "The translational importance of IL-1β as a driver of MDSC propagation is underlined by the finding that in peripheral blood of advanced melanoma patients an increased level of serum IL-1β was associated with the frequency of mo-MDSC and Treg." (PMID 30042333, 2018). "In this study, we demonstrated that NF-κB p65 and p105 were implicated in IL-1β-mediated COX-2 expression in canine melanoma cells." (PMID 30562372, 2018). "It has been reported that the expression levels of the IL-1β gene or protein are associated with the invasiveness and metastasis of melanoma." (PMID 28060744, 2017). "Many of these canonical NF-κB target genes, including IL-1β, IL-6 and IL-8, have been associated with melanoma tumorigenicity, metastasis and angiogenesis, and represent potential targets for therapy." (PMID 27203220, 2016). "We further investigated IL-1β, a cytokine associated with melanoma metastasis as a miR-7-5p-regulated NF-κB target gene." (PMID 27203220, 2016). "Significantly decreased angiogenesis was observed in IL-1β deficient mice injected with either melanoma cells or melanoma cell-containing Matrigel plugs, when compared to wild-type mice." (PMID 24734023, 2014). "Another study found that IL-1β and caspase-1-deficient mice were much less susceptible to melanoma liver metastases by an injected allograft, improving their overall survival." (PMID 24795727, 2014). "The present study shows that, inflammatory macrophages co-cultivated with B16 murine melanoma cells express enhanced VEGF-C mRNA which was found to be associated with an autocrine loop of activity between macrophage IL-1β and TNF-α and their receptors." (PMID 25120672, 2014). "In a study utilizing a B16 melanoma model, IL-1β-deficient mice had remarkably reduced subcutaneous tumor size and lung metastasis compared to wild-type mice." (PMID 24273542, 2013). "This is the case of BRAF mutations in melanoma cells correlating with enhanced levels of immunosuppressive mediators such as IL-6 and IL-10 or anti-apoptotic Bcl-2 and Bcl-xL proteins, regulating the expression of several interleukins, such as IL-8 and IL-1β." (PMID 36768978, 2023). "We noted that loss of IL-1β expression could also enhance LC residency across the melanoma backgrounds, supporting the potential TNF-α–independent activation of LC migration by IL-1β." (PMID 37043573, 2023). "Furthermore, IL-1β has been implicated in the promotion of angiogenesis in several types of malignancies, such as melanoma and fibrosarcoma, potentiating their metastatic potential." (PMID 37511306, 2023). "The downregulation of microphthalmia-associated transcription factor (MITF-M) through IL-1β-induced miR-155 in melanoma cells could represent a mechanism of melanoma immune escape in an inflammatory microenvironment." (PMID 35267528, 2022).
melanoma (continued). "However, following VEM treatment, IL-1β-associated signaling from inflammatory niches is enhanced and confers drug tolerance, suggesting that melanoma-derived IL-1β is a master regulator for drug-resistant cells." (PMID 33396632, 2020). "However, ASC protein expression is repressed in metastatic melanoma compared with primary melanoma, and inflammasome-associated caspase-1 and IL-1β are inhibited when the ASC gene is inhibited in primary and metastatic melanoma cells." (PMID 31242947, 2019). "Finally, cultured RAW 264.7 macrophage and B16F10 melanoma cells were respectively treated with DJ-1 shRNA and recombinant IL-1β to explore underlying molecular mechanisms." (PMID 25706411, 2015). "Furthermore, elevated levels of the proinflammatory proteins present in the “cytokine storm” linked to COVID‐19, such as TNF‐α, IL‐1α, IL‐1β, IL‐6, and ferritin, may have also caused skin depigmentation or hypopigmentation, ultimately resulting in melanoma." (PMID 40270775, 2025). "In addition, some other research studies indicated that inflammasome NLRP3 could make IL-1β secretion increased and T cell responses suppressed, which were associated with tumor development in melanoma." (PMID 36276158, 2022). "We also demonstrated that blockade of IL-1β with neutralizing antibodies can reduce the formation of melanoma nodules (black bars) and lower MDSCs accumulation in lung tissues in DJ-1 KO mice, suggesting that DJ-1 loss-induced MDSCs accumulation and tumor development in lungs are IL-1β dependent." (PMID 25706411, 2015). "This activation of Hippo signaling promotes YAP/TAZ nuclear translocation, enhancing the production and secretion of the tumor-derived cytokine IL-1β, which contributes to vemurafenib resistance in melanoma." (PMID 41145465, 2025). "IL-1β dose-dependently enhanced cell viability in A375R melanoma cells, which is also supported by EdU cell proliferation and colony formation assays." (PMID 41145465, 2025). "Deleting IκBζ in melanoma abrogates the activity and chromatin association of STAT3 and NF-κB, thereby reducing the expression of the pro-proliferative cytokines IL-1β and IL-6, thus impairing melanoma cell growth." (PMID 40562773, 2025). "Another family member, ABCB5, controls IL‐1β secretion in melanoma‐initiating cells through the IL‐1β/IL‐8/CXCR1 cytokine signalling circuit to maintain slow cycling in drug‐resistant cells." (PMID 40665579, 2025). "As the ultimate effector, IL-1β is critical in melanoma resistance against vemurafenib, which endorses the inhibition of IL-1β to be a key strategy for compromising drug resistance." (PMID 41145465, 2025). "To compare these results with another zebrafish melanoma model, we checked the gene expression of il1b and il8 in melanoma biopsies of adult kita:ras zebrafish." (PMID 40449994, 2025). "Certain metastatic melanoma cells exhibit features of an autoinflammatory state by constitutively releasing IL-1β through sustained activation of the inflammasome complex." (PMID 40558540, 2025). "In melanoma, IL-1β secretion is partially regulated by the MAPK/ERK pathway via the transcription factor ATF4." (PMID 40558540, 2025). "In mouse models of subcutaneous melanoma and Lewis lung carcinoma, an IL-1β-based targeted cytokine was shown to safely enhance antitumor CD8+ T cell responses and synergize with other immunotherapies." (PMID 40791595, 2025). "For instance, exogenous IL-1β increases the incidence of spontaneous lung metastasis in melanoma and renal carcinoma cancer cells, and treatment with IL1Ra reduces the incidence of metastasis and tumor growth in vivo." (PMID 39858071, 2025). "Consistently, IL-1β has been reported to have a pro-tumorigenic role in various cancers, such as lung cancer, GI cancer, melanoma and HNC." (PMID 41440367, 2025).